METTL3 (methyltransferase 3, N6-adenosine-methyltransferase complex catalytic subunit)
Diseases named in the same sentence as METTL3 in open-access papers (continued):
Sharing a sentence is not in itself a finding about the gene and the disease.
Obesity (continued). "The specific knockout of METTL3 decreases m6A levels and inhibits critical thermogenic genes, which worsens obesity induced by a high-fat diet." (PMID 41446042, 2025). "Mechanistically, treating the fathers with STM2457, a METTL3 inhibitor, restores obesity-reduced sperm count, and decreases Wt1 N6-methyladenosine level in the mouse testes of the offspring." (PMID 38355624, 2024). "In all three cases, the obesity group had an overexpression trend, with statistically significant overexpression of METTL3 (p = <0.001) when compared with the control group." (PMID 39057082, 2024). "Consistent with other literature in models of longer-term diet-induced obesity in male mice, we also observed a downregulation of Fto and Mettl3 RNA expression, which correspond to a decline in cardiac systolic and diastolic function." (PMID 38363215, 2024). "We found that the mRNA expression of Mettl3 was significantly decreased in the liver of patients with obesity compared to that in lean individuals." (PMID 37335109, 2023). "Adipose Mettl3, Mettl14, and m6A levels are upregulated in obesity, prompting us to test if their molecular targets involved in lipolysis are downregulated in WAT." (PMID 37526326, 2023). "Additional studies are needed to assess the contributions of hyperinsulinemia and other obesogenic factors to upregulation of adipose Mettl3, Mettl14, and m6A‐based epitranscriptomic remodeling in obesity." (PMID 37526326, 2023). "Consistent with our results, Wang revealed that specific deletion of METTL3 in adipose tissue severely promoted high-fat diet (HFD)-induced obesity and IR." (PMID 35933406, 2022). "Dysregulation of N6‐methyladenosine (m6A) methyltransferase components (e.g., Fat mass and obesity‐associated protein [FTO] and methyltransferase‐like 3 [METTL3]) are closely associated with multiple cancer progression, including oral cancer." (PMID 34378866, 2021). "RNA m6A is known to be regulated by the methyltransferase METTL3 (methyltransferase-like 3) and the demethylase FTO (fat mass and obesity-associated protein)." (PMID 33126669, 2020). "Liver METTL14/METTL3/m6A pathways were also activated in obesity (described later)." (PMID 40278833, 2025). "Overall, these findings highlight the importance of METTL3 in regulating brown fat development and metabolism and suggest that targeting this gene may be a promising approach for treating obesity and related metabolic disorders." (PMID 40066222, 2025). "Additionally m6A modification significantly influences in NAFLD and obesity, especially in the function of Mettl3 in myeloid cells." (PMID 41208876, 2025). "For instance, one study found that overexpression of METTL3 in bone marrow monocytes protected mice against osteoporosis induced by estrogen deprivation, while disruption of METTL3 in mice destroyed bone formation, decreased osteogenic differentiation, and improved marrow obesity." (PMID 37215218, 2023). "We found that adipose Mettl3, Mettl4, and m6A levels were upregulated in obesity." (PMID 37526326, 2023). "Apart from tumor-related diseases, “Obesity” and “Atherosclerosis” also appeared frequently in our results, suggesting that METTL3 may influence multiple pathways in other diseases." (PMID 36970605, 2023). "RNAs can be methylated by Methyltransferase-like 3(METTL3), Methyltransferase-like 14 (METTL14) (“writers”), and demethylated by the fat mass- and obesity-associated (FTO) protein and the α-ketoglutarate-dependent dioxygenase alkB homolog 5 (ALKBH5) protein (“erasers”)." (PMID 35346019, 2022). "Genetic studies of depleting either m6A methyltransferases, such as METTL3 and METTL14 or demethylase FTO (fat mass and obesity associated protein), have demonstrated their important roles in controlling cortical development and regulating brain cognitive functions." (PMID 32992647, 2020).
Obesity (continued). "The methyltransferase-like 3 (METTL3)-centered methyltransferase complex catalyzes the addition of the m6A modification, and α-ketoglutarate-dependent dioxygenase alkB homolog 5 (ALKBH5) or fat mass and obesity-associated protein catalyzes the removal from RNA." (PMID 35784864, 2022). "Together, our data highlight the connection between the METTL3/m6A pathway in cardiomyocytes, regulation of FGF1 levels, and modulation of systemic metabolism, overall affecting diet-induced obesity." (PMID 40272887, 2025). "Here, this work shows that adipose Mettl3 and Mettl14 are influenced by fasting, refeeding, and insulin, and are upregulated in high fat diet (HFD) induced obesity." (PMID 37526326, 2023). "BAT-specific knockout of Mettl3 leads to a marked reduction in BAT-mediated adaptive thermogenesis and further promotes high-fat diet (HFD)-induced obesity and systemic insulin resistance." (PMID 32245957, 2020). "BAT-specific knockout of Mettl3 leads to a marked reduction of BAT-mediated adaptive thermogenesis and results in obesity and systemic insulin resistance." (PMID 32245957, 2020). "Although many more investigations are needed, our data collectively suggest that intervention of WTAP, METTL3, METTL14, or an undetermined target of cell cycle-related molecules is a strategy for preventing and treating obesity or obesity-related diseases." (PMID 29866655, 2018). "METTL3 activators may inhibit BMSC adipogenesis and differentiation, offering an effective obesity treatment." (PMID 40428320, 2025). "As a regulatory component of the m6A-methyltransferase machine, WTAP functions as a recruiter to drive the METTL3-METTL14 complex to its mRNA or lncRNA targets, and knockdown of WTAP has been shown to protect from diet-induced obesity, leading to improved insulin sensitivity." (PMID 39054531, 2024). "Additionally, myeloid lineage-restricted deletion of Mettl3 protects mice from age-related and diet-induced development of innate immunity-driven nonalcoholic fatty liver disease (NAFLD) and obesity." (PMID 36225914, 2022). "In addition, IF intervention decreased the m6A methylation levels and METTL3 expression and increased FTO expression in HFD-induced obesity cardiomyopathy." (PMID 35057432, 2022). "Activation of the METTL3 complex by its chemical ligand methyl piperidine-3-carboxylate (MP3C) could promote beige and brown adipose tissue thermogenesis, improving systemic metabolism to alleviate obesity." (PMID 40428320, 2025).
colon carcinoma (51 papers, 2020 to 2026). "Increased expression of methyltransferase-like 3 (METTL3) in tumor-infiltrating myeloid cells (TIM) is associated with poor prognosis in colon cancer patients." (PMID 39867891, 2024). "The increased expression of methyltransferase-like 3 (METTL3) in TIMs has been linked to poor prognosis in patients with colon cancer." (PMID 37646027, 2023). "m6A writer METTL3 was overexpressed in colon cancer and associated with poor prognosis and prevented SOX2 mRNA degradation via m6A modification." (PMID 32993738, 2020). "Additionally, in epigenetic mechanisms, increased expression of METTL3 is associated with poor prognosis in colon cancer patients, and the METTL3-mediated m6A-YTHDF1 axis enhances JAK1 protein translation efficiency and subsequent STAT3 phosphorylation." (PMID 39010066, 2024). "claimed that the increased expression of m6A methyltransferase-like 3 (METTL3) in TIMs was associated with poor prognosis in colon cancer patients, and mechanistically, they found that the accumulated lactate in TME can promote the upregulation of METTL3 in TIMs via inducing lactylation of H3K18." (PMID 37965331, 2023). "Mechanistically, NSUN6 promotes cell cycle progression and cell proliferation of colon cancer through the oncogene METTL3." (PMID 41462962, 2025). "NSUN6 upregulates the expression of the oncogene METTL3 and catalyzes its m5C modification in colon cancer cells." (PMID 41462962, 2025). "Specifically, lactate has been shown to induce methyltransferase-like 3 (METTL3) transcription in tumor-infiltrating myeloid cells (TIMs) via histone H3K18 lactylation, a marker associated with poor prognosis in colon cancer patients." (PMID 40720394, 2025). "In colon cancer cell lines, METTL3 and RBM15 were downregulated, whereas transcript levels of FTO and ALKBH5 were upregulated." (PMID 38665783, 2024). "For instance, METTL3 stabilized the expression of SOX2 through an m6A-IGF2BP2-dependent mechanism in colon cancer." (PMID 36793593, 2023). "It is reported that overexpression of METTL3 (m6A writer) increased the m6A level of colon cancer by enhancing the expression and protein binding effect of lncRNA RP11." (PMID 37614318, 2023). "A murine MC38 colon cancer model was employed to investigate the effect of METTL3-knockdown on PD-1 blockade therapy." (PMID 37402945, 2023). "For example, METTL3 can enhance the expression level of miR-1246 via facilitating the maturation of pri-miR-1246 and, finally, induce malignant metastasis of colon cancer." (PMID 37958388, 2023). "The total RNA content of N6-methyladenosine (M6A) and its key methyltransferase METTL3 expression in colon cancer tissues of oxaliplatin (OX) resistant patients were higher than those of OX-sensitive patients." (PMID 37020597, 2023). "This upregulated methyltransferase-like 3 (METTL3) in infiltrating myeloid cells in colon cancer via H3K18 lactylation, crucial for the transcription of immunosuppressive genes." (PMID 38087370, 2023). "METTL3 was involved in regulating the stemness and chemosensitivity of colon cancer through the upregulation of LGR5." (PMID 36517820, 2022). "First, we found that at the mRNA level, METTL3 expression is significantly higher in cancer tissues compared with that in adjacent normal tissues, for example, in PC or colon cancer." (PMID 36058919, 2022). "We found that METTL3 mRNA expression level in colon cancer tissues was significantly higher than that in adjacent normal tissues (GEO: GSE146771)." (PMID 36058919, 2022). "We then analyzed the PC and also colon cancer data downloaded from the GEO database and found that METTL3 mRNA expression level was higher in malignant epithelial cells compared with normal epithelial cells." (PMID 36058919, 2022).
colon carcinoma (continued). "METTL3 can recognize the m6A modification of pri-miR-1246 to upregulate miR-1246, and thereby promote the proliferation, migration, and invasion of colon cancer cells." (PMID 34497267, 2021). "Through upregulating LGR5, METTL3 participated in regulating stemness and chemosensitivity of colon cancer." (PMID 34345203, 2021). "A higher METTL3 level can promote colon cancer cell tumorgenicity by reducing suppressor of cytokine signaling 2 (SOCS2) expression in cancer cell lines." (PMID 34363020, 2021). "Previous evidence showed that METTL3 promoted miRNA-1246 upregulation and induced metastasis in colon cancer." (PMID 34917614, 2021). "Studies in colon carcinoma have shown that METTL3 stabilizes the expression of SOX2 by an m6A-IGF2BP2-dependent mechanism." (PMID 32391379, 2020). "It has been interestingly reported that lactate upregulates METTL3 expression in colon cancer." (PMID 40448344, 2025). "Accumulation of lactate in the tumor microenvironment (TME) significantly induces the expression of methyltransferase-like 3 (METTL3) in infiltrating myeloid cells in colon cancer mediated through H3K18 lactylation, which is essential for the transcription of immunosuppressive genes in TIM cells." (PMID 37394582, 2023). "As a result, METTL3 promoted the metastasis of colon cancer." (PMID 37614318, 2023). "This prompt METTL3 tumorigenicity of colon cancer cells is a key factor." (PMID 37020597, 2023). "The increase in METTL3 levels may maintain the tumorigenicity of colon cancer cells by inhibiting SOCS2." (PMID 34246319, 2021). "Interestingly, METTL3 can upregulate miR-1246 expression by identifying the m6A modification of pri-miR-1246 to promote the proliferation, migration, and invasion of colon cancer cells." (PMID 34497267, 2021). "For example, the poor prognosis of colon cancer patients can be correlated with the increased expression of METTL3 in tumor-filtrating myeloid cells, which is regulated by Kla and Kla of MOESIN might make more T cells become Treg cells and promote development of tumor." (PMID 38317138, 2024). "The increased expression of METTL3, which mediates m6A modification on JAK1 mRNA, is shown to be correlated with a poor prognosis in colon cancer patients." (PMID 37568073, 2023). "Overexpression of METTL3 represses SOCS2 and promotes LGR5 promoter activity to maintain cell proliferation in colon cancer cells." (PMID 35614935, 2022). "For instance, catalysis of m6A modification is mediated by methyltransferase-like 3 (METTL3), which is expressed at a high level in colon cancer." (PMID 34917614, 2021). "METTL3‐mediated m6A methylation of CBX8 mRNA and IGF2BP1‐induced mRNA stability coordinately sustain CBX expression in colon cancer." (PMID 33029866, 2020). "METTL3 drives the ectopic expression of CBX8 in an m6A‐dependent manner, which obviates the sensitivity of colon cancer cells to chemotherapy of CPT‐11 and L‐OHP." (PMID 33029866, 2020). "Lactate accumulated in the colon cancer microenvironment is taken up by tumor‐infiltrating myeloid cells (TIMs) and histone H3K18 lactylation activates METTL3 transcription, resulting in increased METTL3 expression." (PMID 40448344, 2025).
colon carcinoma (continued). "In addition, METTL3 increases the expression of PTTG3P through an m6A/IGF2BP2-dependent mechanism and regulates the PTTG3P/YAP1 axis to induce colon cancer cell proliferation and promote colon cancer progression." (PMID 35614935, 2022). "In addition, METTL3/WTAP and IGF2BP3 elevated the expression of β-catenin downstream gene, CCND1, via writing and reading the m6A modification on it to promote colon cancer progression." (PMID 34315512, 2021). "At present, only METTL3, YTHDF1, YTHDF3 was researched in colon cancer, other roles of m6A enzymes remain unclear." (PMID 32993738, 2020).
ovarian carcinoma (50 papers, 2019 to 2026). A malignant neoplasm originating from the surface ovarian epithelium. "According to existing studies, diabetic nephropathy, diabetic retinopathy, ovarian cancer, hypoxic pulmonary hypertension, prostate enlargement, and some other diseases were associated with METTL3-PTEN pathway." (PMID 36970605, 2023). "Further, the Kaplan–Meier analysis showed that METTL3 high expression was associated with poor prognosis of ovarian cancer." (PMID 34497267, 2021). "METTL3 is highly expressed in ovarian cancer, and the expression of METTL3 is significantly associated with grade, pT status, pN/pM status and International Federation of Obstetrics and Gynecology (FIGO) stage." (PMID 31808521, 2019). "Additionally, high expression of METTL3 has been linked to poor survival prognosis in ovarian cancer patients." (PMID 37684273, 2023). "Moreover, METTL3 expression is upregulated in ovarian cancer and is associated with advanced tumor grades and stages, lymph node and distant metastases, the International Federation of Gynecology and Obstetrics stage, and overall patient survival." (PMID 35251990, 2022). "In ovarian cancer, the abnormal expression of m6A modification enzymes (such as METTL3) is related to microbiota disorders." (PMID 40732683, 2025). "In ovarian cancer, m6A regulators such as METTL3 and ALKBH5 modulate immune checkpoint expression, including PD-L1, impacting T-cell function and infiltration." (PMID 41029427, 2025). "In ovarian cancer, RRGs like DNMT1 and METTL3 are implicated in resistance to cisplatin and paclitaxel, while m1A regulators such as TRMT10C influence tumor proliferation." (PMID 41029427, 2025). "METTL3 was shown to promote ovarian cancer cell proliferation, invasion, and migration through targeting pri-miRNA 126-5p, lncRNA RHPN1 antisense RNA 1 (head to head) (RHPN1-AS1) and AXL receptor tyrosine kinase (AXL) mRNA18,43,44." (PMID 38714753, 2024). "Ultimately, our findings confirm that EZMLD induces apoptosis in ovarian cancer cells through the mechanism of METTL3 and METTL14 methyltransferases, which mediate KRT8 m6A methylation modification." (PMID 39103890, 2024). "Our study demonstrates that EZMLD exerts significant antitumor effects on SKOV3 ovarian cancer cells in vitro and in vivo by modulating METTL3/14 expression." (PMID 39103890, 2024). "In ovarian cancer cells, METTL3 was found to inhibit GC cell proliferation by inactivating the AKT pathway, while WTAP stimulated AKT pathway activation, leading to enhanced proliferation and migration." (PMID 38649363, 2024). "The abnormal expression of m6A-related regulatory enzymes including METTL3, FTO, ALKBH5, IGF2BP1, YTHDF1, and YTHDF2 is closely linked with the growth, metastasis, invasion, and chemotherapy resistance in ovarian cancer." (PMID 37781028, 2023). "METTL3-mediated m6A modification of lncRNA RHPN6-AS1 enhances cisplatin resistance in ovarian cancer through activation of the PI3K/AKT pathway." (PMID 37194218, 2023). "The METTL3/YTHDF2 axis can lead to cisplatin resistance of ovarian cancer by regulating the mRNA stability of IFFO1 in an m6A-dependent manner and inhibiting IFFO1 expression." (PMID 37319315, 2023). "A meta-analysis showed that aberrant METTL3 expression in different cancers, including ovarian cancer, tended to predict poor prognosis." (PMID 37194218, 2023). "METTL3-mediated miR-126-5p maturation promotes the progression of ovarian cancer through the PI3K/Akt/mTOR pathway mediated by PTEN." (PMID 35945641, 2022). "Using immunohistochemistry on 52 patient samples, in one study METTL3 was highly expressed in ovarian cancer tissues compared to adjacent normal tissues, and was significantly correlated to tumor grade." (PMID 36008936, 2022).